AGER (advanced glycosylation end-product specific receptor)
Diseases named in the same sentence as AGER in open-access papers (continued):
Sharing a sentence is not in itself a finding about the gene and the disease.
cervical squamous cancer (2 papers, 2018 to 2022). "Collectively, these data suggested that AGER may be implicated in the development and progression of cervical squamous cancer." (PMID 29298878, 2018). "AGER protein primarily localized in the cytoplasm and cytomembrane of cervical squamous cancer cells." (PMID 29298878, 2018). "Blockage of AGER with multiple siRNAs suppressed proliferation, stimulated apoptosis, inhibited migration of cervical squamous cancer cells." (PMID 29298878, 2018). "To further elucidate its role in the progression of cervical squamous cancer, we silenced the expression of AGER by RNAi approach and overexpressed AGER via lentivirus infection." (PMID 29298878, 2018). "Initially, the localization of AGER protein in four cervical squamous cancer cells (SiHa, C33A, Caski, and MS751) was determined using immunocytochemical assay." (PMID 29298878, 2018). "Along similar lines, our previous study documented that AGER protein expression was gradually increased from chronic cervicitis to cervical intraepithelial neoplasia and to squamous cervical cancer, and higher levels of AGER were related to histological differentiation." (PMID 29298878, 2018). "Furthermore, high AGER protein levels in squamous cervical cancer significantly correlated with tumor differentiation." (PMID 29298878, 2018). "We have previously reported that AGER was overexpressed in squamous cervical cancer." (PMID 29298878, 2018). "Thus, AGER may promote cervical squamous cancer growth via suppressing apoptosis." (PMID 29298878, 2018).
endotoxemia (2 papers, 2019 to 2023). "A recent study shows that global knockout of AGER improves survival in mice treated with poly(I:C) followed by LPS, indicating a pathologic role of AGER in the regulation of caspase-11-dependent endotoxemia." (PMID 31440260, 2019).
morbid obesity (2 papers, 2021 to 2023). An excess of body weight, normally defined as an individual with a body mass index greater than 35 or a body weight greater than one hundred percent of ideal body weight. "Our first hypothesis was that compared to obese subjects, AGER/DIAPH1 expression in adipose tissue would be significantly higher in subjects with morbid obesity whereas lower expression of mRNA transcripts encoding the AGE-detoxifier enzyme GLO1 was predicted in those individuals." (PMID 34103691, 2021).
pancreatic ductal adenocarcinoma (2 papers, 2018 to 2021). An infiltrating adenocarcinoma that arises from the epithelial cells of the pancreas. "AGER-deficient mice presented a decreased tendency for breast tumor growth and AGER gene deletion inhibited the development of pancreatic intraepithelial neoplasia and progression to pancreatic ductal adenocarcinoma in a murine model." (PMID 29298878, 2018).
psoriasis (2 papers, 2009 to 2024). An autoimmune condition characterized by red, well-delineated plaques with silvery scales that are usually on the extensor surfaces and scalp. "Likewise, genes located farther from HLA-C at the centromeric end, including TNF-α (tumor necrosis factor-alpha), AGER (receptor of advanced glycosylation end product-specific receptor), HLA-DRB1, HLA-DQA1 and HLA-DQB1, have also been found to be associated with psoriasis." (PMID 19680446, 2009).
sarcoidosis (2 papers, 2017 to 2025). Sarcoidosis is a multisystemic disorder of unknown cause characterized by the formation of immune granulomas in involved organs. "Among the twelve common DEGs, SALL4, WNT10A, RASAL1, CAMK2B were significantly upregulated while GADD45B, KLF4, OLR1, CSF3, WIF1, RAMP3 and AGER downregulated in both sarcoidosis and LC as compared to the controls." (PMID 40797277, 2025). "To detect variants predisposing to sarcoidosis and to identify genetic differences between patient subgroups, we studied four genes in the MHC Class III region (LTA, TNF, AGER, BTNL2) and HLA-DRA with tag-SNPs and their relation to HLA-DRB1 alleles." (PMID 28469621, 2017).
schizophrenia (2 papers, 2017 to 2025). A major psychotic disorder characterized by abnormalities in the perception or expression of reality. "AGER (Tier A evidence for schizophrenia) and CD40 (Tier B evidence for both schizophrenia and bipolar disorder) have drugs in advanced clinical trials." (PMID 40281223, 2025). "Among them, AGER (schizophrenia), CD40 (schizophrenia & bipolar), TNFRSF17 (schizophrenia), ACE (schizophrenia & Alzheimer’s) and SEPRING1 (schizophrenia) have drugs approved or in advanced clinical trials for several indications including cardiovascular and autoimmune conditions." (PMID 40281223, 2025). "It is worth noting here that although we had evidence from blood pQTLs and eQTLs for a potential effect of AGER on schizophrenia, we did not test for colocalisation between the QTLs due to the lead SNPs residing in the MHC region." (PMID 40281223, 2025). "Specifically, AGER, PDIA3 and NAGA appeared to have an effect on schizophrenia." (PMID 40281223, 2025).
Adult onset (1 paper, 2023). Onset of disease manifestations in adulthood, defined here as at the age of 16 years or later. "In conclusion, this study provides evidence that rare and low-frequency coding variants associated with adult-onset MS (PRF1) and within the MHC region (BRD2 and AGER) are associated with POMS susceptibility." (PMID 36755464, 2023). "These included variants within PRF1, a gene that was previously identified as associated with adult-onset MS, and two genes in the MHC region (BRD2 and AGER)." (PMID 36755464, 2023).
allergic disease (1 paper, 2024). An immune response that occurs following re-exposure to an innocuous antigen, and that requires the presence of existing antibodies against that antigen. "Similarly, we fine-mapped MHC region for other allergic diseases and found potential key genes including HLA family and AGER." (PMID 38639992, 2024).
cervical intraepithelial neoplasia (1 paper, 2018). "Our previous study reported that AGER was progressively up-regulated from cervicitis to cervical intraepithelial neoplasia and cancer." (PMID 29298878, 2018).
cervicitis (1 paper, 2018). An acute or chronic inflammatory process that affects the cervix. "However, the molecular mechanism responsible for the role of AGER in such malignancy and the involvement of synergistic effects of AGER and HPV on the squamous cervical carcinogenesis or progression needs further investigation." (PMID 29298878, 2018).
cholesteatoma (1 paper, 2022). A pathologic process characterized by the proliferation of keratinizing squamous epithelium resulting in the accumulation of keratin and cells in the middle ear and/or mastoid. "AGER contributes to cholesteatoma pathogenesis by inducing cholesteatoma tissue proliferation and migration and releasing proinflammatory cytokines." (PMID 35273637, 2022).
chronic lymphocytic leukaemia (1 paper, 2024). "This integrative analysis identified genes whose dysregulation may explain the links between JIA and associated traits, such as autoimmune/inflammatory diseases (genes at 6p22.1 locus), Hodgkin lymphoma (genes at 6p21.3 [FKBPL, PBX2, AGER]), and chronic lymphocytic leukemia (BAK1)." (PMID 39175752, 2024). "Notably, in addition to HLA class II genes (which might contribute to chronic inflammation), we found a distinct association between JIA and Hodgkin lymphoma through a set of genes in 6p21.3 (FKBPL, PBX2, AGER); and chronic lymphocytic leukaemia through the BAK1 gene." (PMID 39175752, 2024).
colorectal tumor (1 paper, 2023). "The expression of advanced glycosylation end-product specific receptor (AGER) is significantly lower in the colorectal tumor epithelia compared to paired normal mucosa." (PMID 37438760, 2023).
fibrosis (1 paper, 2024). the formation of excess fibrous connective tissue in an organ or tissue in a reparative or reactive process. "Finally, the disease gene-association analysis on the DEGs without the respiratory tract disease filter showed that six DEGs (namely, ACTG2, AGER, COL1A1, COL3A1, IGF1, and SPP1) were associated with fibrosis." (PMID 39944354, 2024).
Hypoglycemia (1 paper, 2024). A decreased concentration of glucose in the blood. "Furthermore, hypoglycemia is associated with high expression of the receptor for advanced glycation end products (RAGE) in T1D adolescent donors compared to non-diabetic adolescent donors, with AGER being the most important predictor of the islet’s glucagon levels." (PMID 39594662, 2024).
inflammatory breast carcinoma (1 paper, 2025). An advanced, invasive breast adenocarcinoma characterized by the presence of distinct changes in the overlying skin. "Our study provides novel insights into the significance of TLR4 and AGER in inflammatory breast cancer." (PMID 40647480, 2025). "Understanding the roles of TLR4 and AGER could offer new targets for future therapies and improve outcomes for patients with inflammatory breast cancer." (PMID 40647480, 2025). "However, the role of TLR4 and AGER, specifically in inflammatory breast carcinomas, has not been fully elucidated." (PMID 40647480, 2025).
iridocyclitis (1 paper, 2024). "Lastly, 3 plasma proteins share the same genetic variant with chronic iridocyclitis: AIF1 (coloc.abf-PPH4 = 1.000), AGER (coloc.abf-PPH4 = 0.887), and COL11A2 (coloc.abf-PPH4 = 0.872)." (PMID 38475831, 2024).
leukemia (1 paper, 2021). A malignant (clonal) hematologic disorder, involving hematopoietic stem cells and characterized by the presence of primitive or atypical myeloid or lymphoid cells in the bone marrow and the blood. "In addition, it has been proven that in leukemia cells, intracellular HMGB1-triggered ferroptosis also engaged two other proteins, transferrin receptor (TFRC) and advanced glycosylation end-product specific receptor (AGER)." (PMID 33578654, 2021).
lymph node metastasis (1 paper, 2023).
oral cancer (1 paper, 2018). "Suppressing AGER reduced cell migration via the regulation of extracellular signal regulated kinase, and downstream pathways in human oral cancer cells." (PMID 29298878, 2018).
prediabetes (1 paper, 2022). "Even though AGER gene suppression was repetitively shown in both our and previous studies, the underlying mechanism leading to the suppression of AGER in prediabetes remains to be elucidated." (PMID 35237235, 2022). "A level of serum pentosidine lower than the threshold of 2.1 ng/ml was found to be associated with lower AGER expression level and may relate to the preservation of osteogenic differentiation in prediabetes." (PMID 35237235, 2022). "Interestingly, the AGER expression was significantly suppressed in individuals with prediabetes compared to age- and pentosidine-matched normoglycemic individuals (0.5 ± 0.6 vs 1.0 ± 0.0, p = 0.003)." (PMID 35237235, 2022). "Our results regarding AGER suppression in prediabetes were consistent with a previous report." (PMID 35237235, 2022). "Since the suppression of AGER conceivably contributes to a decrease in cellular apoptosis and preservation of osteogenic differentiation in prediabetes, the suppression of AGER would be a good predictive factor for the maintenance of skeletal integrity in prediabetes." (PMID 35237235, 2022).
tumor (88 papers, 2009 to 2026). "Many of these (DLK1, GAB2, BOLA2B, AOX1 and AGER) were closely related to cell proliferation and tumor progression, and associated with poor prognosis in HCC." (PMID 35331184, 2022). "Furthermore, we used the TIMER network resource to explicate the associations of AGER and important components of the tumor microenvironment (tumor-infiltrating immune cells)." (PMID 37497166, 2023). "Although further studies are warranted to clarify the causal relationship, our results suggest that the AGER rs2070600 polymorphism is a potential genetic marker for tumor-related inflammatory conditions and a poor prognosis in patients with metastatic lung adenocarcinoma." (PMID 29212235, 2017). "Targeted small-molecule antagonists of AGER show promise in disrupting tumor-promoting AGER-mediated signaling." (PMID 40563443, 2025). "AGER, the receptor for advanced glycation end products, plays a crucial role in tumor angiogenesis and can be used as a prognostic biomarker for ccRCC." (PMID 40535574, 2025). "HMGB1 binds to advanced glycosylation end product‐specific receptor (AGER) to release TNF‐α synergistically for anti‐tumour immunotherapy." (PMID 38652105, 2024). "The expression of HMGN1, HSP90AA1, BCL2, and AGER was verified in TCGA and GTEx databases, and HMGN1, HSP90AA1 and AGER were found to be highly expressed in tumor tissues." (PMID 38713284, 2024). "Although AGER has multitudinous functions in the tumor microenvironment, numerous mechanisms are still unclear, especially the potential mechanism between DNA methylation and lymphocyte infiltration in LUAD and LUSC." (PMID 37497166, 2023). "We investigated the correlation between AGER expression level and 28 tumor immune infiltrating lymphocyte subtypes." (PMID 37497166, 2023). "TIMER platform and TISIDB website were used to show the correlation between AGER expression and tumor immune cell infiltration level." (PMID 37497166, 2023). "Previous studies reported that LINC00173 acted as a tumor suppressor by inhibiting the miR-182-5p-regulated AGER/NF-κB pathway to restrain cell proliferation and migration in NSCLC." (PMID 36627670, 2023). "Mediated by AGER, this uptake ultimately resulted in an increase of macrophages of M2 phenotype, accelerating tumor growth." (PMID 35432535, 2022). "The mRNA level of CR2, INSL4, FGF5, RAET1L and TNFRSF13B was upregulated in LUAD tumor tissues compared with paired normal tissues whereas AGER was downregulated." (PMID 36294477, 2022). "In this context, KRAS-G12D can be released within exosomes by ferroptotic cancer cells and taken up by macrophages through an AGER-dependent mechanism, resulting in the polarization of macrophages to an M2 phenotype and promotion of tumor growth." (PMID 34796174, 2021). "Other immune-related genes of the nine-IRGP signature, including BTN3A3, RORC, and AGER, participate in promoting tumorigenesis, decreasing efficacy of immunotherapy, and preventing tumor immune killing through a variety of immunological mechanisms." (PMID 32211443, 2020). "It has also been well documented that AGER regulates cancer cell motility and drives tumor metastasis through its ligand." (PMID 29298878, 2018). "Targeting the AGER-mediated polarization pathway through molecular drug design could serve as a promising approach to inhibiting tumor progression." (PMID 39893499, 2025). "Additionally, insulin growth factor-1 (IGF-1)-dependent activation of the AGER signaling in adjacent endothelial cells fuels angiocrine mechanisms and tumor progression." (PMID 40647480, 2025). "The coordinated downregulation of KLF4, OLR1, CSF3, WIF1, RAMP3, and AGER, may impair tumor-suppressive mechanisms, thereby facilitating cancer progression, including enhanced tumor growth, migration, invasion, and metastasis." (PMID 40797277, 2025).
tumor (continued). "Toll-like receptor type 4 (TLR4) and Advanced Glycation End Products Receptor (AGER/RAGE) have been implicated in breast cancer, and have been shown to promote tumor growth, metastasis, and resistance to therapy by modulating the tumor microenvironment and inflammatory pathways." (PMID 40647480, 2025). "Additionally, results from the proteomic analysis of serum from tumor-bearing mice indicate that AGER inhibition affects metastatic mechanisms by decreasing the expression of STAT3 and AKT." (PMID 40647480, 2025). "Thus, we raise a possible regulatory mechanism of AGER DNA methylation and tumor-infiltrating lymphocytes which influence prognoses of LUAD and LUSC to some extent." (PMID 37497166, 2023). "Further analysis showed that AGER DNA methylation may be correlated with tumor-infiltrating lymphocytes, especially CD4+ T cells, active CD8+ T cells, memory B cells, natural killer T cells, and type 2 T helper cells." (PMID 37497166, 2023). "Consequently, our study provides insight into a novel role of AGER expression and DNA methylation in tumor immune infiltration." (PMID 37497166, 2023). "Furthermore, knockdown of AGER decreases both the quantity and suppressive activity of tumor-induced myeloid-derived suppressor cells (MDSCs)." (PMID 35372081, 2022). "Overall, AGER, PECAM1, and SLC2A1 were validated for their expression in normal and LUAD tumor IHC samples, showing that the candidate gene biomarkers can function as biologically significant biomarkers to aid in the detection of early-stage LUAD." (PMID 40563443, 2025). "Out of 21 ICD-related genes with notably different expressions, seven genes, namely ROCK1, BCL2, TLR2, TLR9, AGER, CASR, and P2RX7, were found to have decreased expression in tumor samples, while the rest were upregulated." (PMID 37932362, 2023). "We validated the gene expression levels of AGER, DGKK, ASB2, TCP10L2, Lnc-ALCAM-3, and Lnc-TGFBR2-1 in HCC tumour tissue samples from mice treated with high-dose ascorbate by qPCR." (PMID 31754384, 2019). "IHC analysis also revealed that AGER had no staining in the LUAD tumor and had high staining in the normal lung, validating the downregulation of the gene in LUAD." (PMID 40563443, 2025). "The role of AGER role in tumor angiogenesis could be influencing EMCN expression in endothelial cells, thereby affecting tumor microenvironment and vascularization, which is critical for tumor growth and metastasis." (PMID 40535574, 2025). "Assessment of epithelial marker genes showed similar expression scores across fresh and FFPE tissue samples, as EPCAM, KRT5, SCGB3A2, FOXJ1, AGER and SFTPC marked tumor epithelial, Basal, Transitional, Ciliated, AT1, and AT2 cells, respectively, across the datasets." (PMID 38300468, 2024). "In our work, Tumor Immune Estimation Resource (TIMER), Gene Expression Profiling Interactive Analysis (GEPIA), UALCAN, and Kaplan–Meier plotter databases were used to demonstrate AGER expression level and its correlation with the prognosis." (PMID 37497166, 2023). "AGER may be a candidate for the prognostic biomarker of LUAD and LUSC related to tumor immune microenvironment." (PMID 37497166, 2023). "Immunostaining only detected expression of the club cell marker CC10 (also known as SCGB1A1) and not the AT1 marker AGER on tumor sections." (PMID 35577801, 2022). "Tumor cells express scavenger receptor genes, but not AGER and TLR4 at significant levels, suggesting that these cells are primarily targeted by S100A8/A9 heterodimers." (PMID 27215396, 2016). "However, AGER expression negatively impacted metastasis-free survival in non-IBC subjects, suggesting that each pattern recognition receptor differentially contributes to tumor pathogenesis." (PMID 40647480, 2025). "Also, AGER and IL20RB have been reported as tumor promoters in ccRCC." (PMID 33681201, 2021).